DDX11 (DEAD/H-box helicase 11)
Description:
DNA-dependent ATPase and ATP-dependent DNA helicase that participates in various functions in genomic stability, including DNA replication, DNA repair and heterochromatin organization as well as in ribosomal RNA synthesis. Its double-stranded DNA helicase activity requires either a minimal 5'-single-stranded tail length of approximately 15 nt (flap substrates) or 10 nt length single-stranded gapped DNA substrates of a partial duplex DNA structure for helicase loading and translocation along DNA in a 5' to 3' direction. The helicase activity is capable of displacing duplex regions up to 100 bp, which can be extended up to 500 bp by the replication protein A (RPA) or the cohesion CTF18-replication factor C (Ctf18-RFC) complex activities. Also shows ATPase- and helicase activities on substrates that mimic key DNA intermediates of replication, repair and homologous recombination reactions, including forked duplex, anti-parallel G-quadruplex and three-stranded D-loop DNA molecules. Plays a role in DNA double-strand break (DSB) repair at the DNA replication fork during DNA replication recovery from DNA damage. Recruited with TIMELESS factor upon DNA-replication stress response at DNA replication fork to preserve replication fork progression, and hence ensure DNA replication fidelity. Also cooperates with TIMELESS factor during DNA replication to regulate proper sister chromatid cohesion and mitotic chromosome segregation. Stimulates 5'-single-stranded DNA flap endonuclease activity of FEN1 in an ATP- and helicase-independent manner; and hence it may contribute in Okazaki fragment processing at DNA replication fork during lagging strand DNA synthesis. Its ability to function at DNA replication fork is modulated by its binding to long non-coding RNA (lncRNA) cohesion regulator non-coding RNA DDX11-AS1/CONCR, which is able to increase both DDX11 ATPase activity and binding to DNA replicating regions. Also plays a role in heterochromatin organization. Involved in rRNA transcription activation through binding to active hypomethylated rDNA gene loci by recruiting UBTF and the RNA polymerase Pol I transcriptional machinery. Plays a role in embryonic development and prevention of aneuploidy (By similarity). Involved in melanoma cell proliferation and survival. Associates with chromatin at DNA replication fork regions. Binds to single- and double-stranded DNAs. (Microbial infection) Required for bovine papillomavirus type 1 regulatory protein E2 loading onto mitotic chromosomes during DNA replication for the viral genome to be maintained and segregated.
Synonyms: KRG-2; CHL1; CHLR1; KRG2; WABS
Tractability: PROTAC: ubiquitination databases record sites on it.
Gene: Protein-coding gene on chromosome 12 (31,073,282 to 31,104,811, forward strand). Ensembl gene ENSG00000013573.
Subcellular location: Nucleus; Nucleus, nucleolus; Cytoplasm, cytoskeleton, spindle pole; Midbody; Cytoplasm, cytoskeleton, microtubule organizing center, centrosome; Chromosome
Subcellular location (Human Protein Atlas): Nucleoplasm; Nucleoli
Pathways (Reactome):
Cellular responses to stimuli: XBP1(S) activates chaperone genes
Gene Ontology:
Molecular function: 5'-3' DNA helicase activity; ATP hydrolysis activity; ATP-dependent activity, acting on DNA; ATP-dependent activity, acting on RNA; chromatin binding; DNA binding; DNA helicase activity; DNA replication origin binding; double-stranded DNA binding; G-quadruplex DNA binding; G-quadruplex unwinding activity; helicase activity; protein binding; single-stranded DNA binding; single-stranded RNA binding; triplex DNA binding; ATP binding; hydrolase activity, acting on acid anhydrides, in phosphorus-containing anhydrides; nucleic acid binding
Biological process: cellular response to bleomycin; cellular response to cisplatin; cellular response to hydroxyurea; DNA damage response; negative regulation of protein binding; nucleolar chromatin organization; positive regulation of chromatin binding; positive regulation of double-strand break repair; positive regulation of sister chromatid cohesion; positive regulation of transcription of nucleolar large rRNA by RNA polymerase I; replication fork processing; sister chromatid cohesion; establishment of sister chromatid cohesion; DNA metabolic process
Cellular component: centrosome; chromatin; chromosome; extracellular exosome; midbody; mitotic cohesin complex; nucleolus; nucleoplasm; nucleus; spindle pole
Genetic constraint (gnomAD): Loss-of-function variants: 72 observed, 112.2 expected, observed/expected ratio (o/e) 0.64, 90% interval 0.53 to 0.78. The upper end of that interval is the gene's LOEUF score, 0.78, which puts it in group 3 of 6, group 1 being the genes least tolerant of losing a copy. Missense variants: 882 observed, 1,089 expected, observed/expected ratio (o/e) 0.81, 90% interval 0.76 to 0.86. Synonymous variants: 346 observed, 409.63 expected, observed/expected ratio (o/e) 0.84, 90% interval 0.77 to 0.92.
Gene-disease validity (ClinGen):
ClinGen rates the evidence that DDX11 causes each of these diseases.
Warsaw breakage syndrome (autosomal recessive): Definitive. A syndrome mainly characterized by severe growth retardation and microcephaly.
Homologues: Orthologues: macaque DDX11 (90% identical), chimpanzee DDX11 (87% identical), pig DDX11 (84% identical), dog DDX11 (83% identical), mouse Ddx11 (79% identical), rat Ddx11 (78% identical), guinea pig DDX11 (75% identical), tropical clawed frog ddx11 (64% identical), zebrafish ddx11 (59% identical), Drosophila melanogaster CG11403 (38% identical), Caenorhabditis elegans chl-1 (33% identical). Paralogues in human: BRIP1 (24% identical), RTEL1 (24% identical), ERCC2 (20% identical).
Diseases named in the same sentence as DDX11 in open-access papers:
DDX11 is named in the same sentence as 54 diseases in open-access papers, as found by Europe PMC text mining. Sharing a sentence is not in itself a finding about the gene and the disease. The quoted sentences say what the papers report.
Warsaw breakage syndrome (39 papers, 2013 to 2026). "DDX11 is primarily recognized for its role in maintaining sister chromatid cohesion as an inactivating mutation results in the cohesinopathy called Warsaw Breakage Syndrome." (PMID 36968611, 2023). "For instance, mutations in DDX11 (ChlR1) are associated with Warsaw Breakage syndrome (WBS) and Roberts syndrome." (PMID 36761420, 2022). "ChlR1/DDX11 mutation leads not only to cohesion defects, but also developmental maladies such as Warsaw breakage syndrome." (PMID 35456431, 2022). "Warsaw breakage syndrome, with less than a dozen patients identified, is caused by a mutation in the G4-DNA helicase DDX11." (PMID 34139671, 2021). "Warsaw breakage syndrome is a developmental disorder caused by mutations in the conserved DDX11 DNA helicase." (PMID 33879618, 2021). "DDX11 mutations cause the Warsaw Breakage Syndrome (WABS), which shows features of genome instability similar to Fanconi anemia (FA)." (PMID 34299244, 2021). "Mutation of DDX11 is considered as the cause of rare genetic disease Warsaw breakage syndrome (WABS)." (PMID 33614480, 2020). "The iron–sulfur (FeS) cluster helicase DDX11 is associated with a human disorder termed Warsaw Breakage Syndrome." (PMID 32071282, 2020). "Discovery in 2010 of the linkage between DDX11 gene mutations and Warsaw breakage syndrome, a rare genetic disease, highlighted for the first time its medical relevance." (PMID 30469382, 2018). "Mutations of human DDX11 are indeed associated with the rare genetic disorder named Warsaw breakage syndrome, showing both chromosomal breakages and chromatid cohesion defects." (PMID 30469382, 2018). "Autosomal recessive mutations of the DDX11 gene are responsible for a rare cohesinopathy, named Warsaw breakage syndrome (WABS)." (PMID 30469382, 2018). "Recessive bi-allelic mutations in the Fe-S helicase DDX11/ChlR1 are linked to the rare genetic disorder Warsaw Breakage syndrome characterized by microcephaly and congenital abnormalities, as well as defective sister chromatid cohesion at the cellular level." (PMID 28594346, 2017). "Mutations in CHL1 human homologs BACH1/BRIP/FANCJ and ChlR1/DDX11 helicases collectively result in Warsaw Breakage Syndrome, Fanconi anemia, breast and ovarian cancers." (PMID 29186203, 2017). "Mutations in the human ChlR1 (DDX11) gene are associated with a unique genetic disorder known as Warsaw Breakage Syndrome, which is characterized by cellular defects in genome maintenance." (PMID 26474416, 2015). "Warsaw breakage syndrome (WABS) is caused by defective DDX11, a DNA helicase that is essential for chromatid cohesion." (PMID 26423134, 2015). "Loss of DDX11 in humans leads to the rare cohesinopathy Warsaw breakage syndrome." (PMID 38478595, 2024). "Additionally, mutations in human DDX11 are associated with a rare cohesinopathy hereditary disease known as Warsaw breakage syndrome (WABS)." (PMID 36892674, 2023). "The DDX11 variant associated with Warsaw Breakage Syndrome (R263Q) cannot bind an Fe-S cluster." (PMID 36968611, 2023). "Chl1/DDX11—Mutations in DDX11 underlie the cohesinopathy Warsaw breakage syndrome." (PMID 34943967, 2021). "Warsaw Breakage Syndrome (WABS) results from bi-allelic mutations in the DNA helicase DDX11." (PMID 31935221, 2020). "Warsaw Breakage Syndrome (WABS) is an ultra rare cohesinopathy caused by biallelic mutation of DDX11 gene." (PMID 30924321, 2019). "Warsaw breakage syndrome (WABS) is a rare autosomal recessive disease due to homozygous mutations in the gene coding for DDX11." (PMID 30469382, 2018). "DDX11 (also named ChlR1) is a super-family 2 Fe-S cluster-containing DNA helicase implicated in Warsaw breakage syndrome (WABS)." (PMID 30303954, 2018). "Recently, mutations in the XPD family helicase gene DDX11 were identified in the hereditary disorder Warsaw Breakage Syndrome (WABS)." (PMID 30544644, 2018).
Warsaw breakage syndrome (continued). "Warsaw breakage syndrome (WABS) is a very rare autosomal recessive disease, due to biallelic mutations of the gene coding for the DDX11 DNA helicase." (PMID 33669056, 2021). "The expression of DDX11 is dysregulated and has a significant effect on the progression of many tumors such as lung adenocarcinoma, melanoma and Warsaw breakage Syndrome." (PMID 34094926, 2021). "Herein, we aimed to review recent findings about the human genome stability maintenance DNA helicase DDX11 and the related rare genetic disease, Warsaw breakage syndrome, which is characterized by sister chromatid cohesion anomalies and developmental defects." (PMID 33669056, 2021). "DDX11 is genetically linked to the Warsaw breakage syndrome (WABS), a rare hereditary disease." (PMID 30303954, 2018). "The issue is a critical one given that mutations in the Chl1 human homologs ChlR1/DDX11 and BACH1/BRIP1/FANCJ collectively result in Warsaw Breakage Syndrome, Fanconi anemia, cell aneuploidy and breast and ovarian cancers." (PMID 29186203, 2017). "Roberts syndrome/SC phocomelia (RBS), and Warsaw Breakage syndrome (WABS) are two recessive cohesinopathies, caused by homozygous mutations in single genes, ESCO2 and DDX11/CHLR1, respectively." (PMID 27636994, 2016). "Chl1 is of further import because it is the homolog of both ChlR1/DDX11 and BACH1/BRIP/FANCJ, mutations in which result in Warsaw Breakage Syndrome and both Fanconi anemia and breast and ovarian cancers, respectively." (PMID 24086532, 2013). "For example, Apcin effectiveness is enhanced in cells carrying defective sister chromatid cohesion, that also characterize a subgroup of AML patients, as shown by using cellular models of Warsaw breakage syndrome with defective function of the DNA helicase DDX11." (PMID 35490245, 2022). "Besides, hypotheses formulated about the etiopathogenesis of Warsaw breakage syndrome (WABS), the hereditary syndrome due to biallelic mutations of the DDX11 gene, are discussed in light of recent findings of its multi-faceted cellular role." (PMID 33669056, 2021). "FANCJ R279Q was included because the homologous arginine residues in the related helicases DDX11 and XPD are required for FeS cluster stabilisation, and mutations causing their alteration are linked to Warsaw Breakage Syndrome and Trichothiodystrophy, respectively." (PMID 32542039, 2020). "Mutations of DDX11 are linked to Warsaw Breakage syndrome, but not frequent in human cancers." (PMID 33614480, 2020). "Warsaw Breakage Syndrome (WABS; OMIM #613398) is an ultra rare genetic disease caused by biallelic mutations of the DDX11 (DEAD/H box‐11) gene." (PMID 30924321, 2019).
melanoma (19 papers, 2012 to 2025). A malignant, usually aggressive tumor composed of atypical, neoplastic melanocytes. "DDX11 has been shown to be associated with the progression of multiple cancers, including melanoma, lung adenocarcinoma, and hepatocellular carcinoma." (PMID 39767827, 2024). "DDX11 functions as an FA pathway backup, and its deficiency leads to impaired strand repair, while its inhibition caused apoptosis in melanomas." (PMID 34299244, 2021). "Recently, DDX11 has been linked to the progression of multiple cancers, including melanoma and lung cancer." (PMID 32332880, 2020). "In particular, we document that inhibiting DDX11 expression causes substantial chromosome segregation defects and telomere shortening, major inhibition of melanoma cell proliferation, and rapid and massive melanoma cell apoptosis." (PMID 23116066, 2012). "Thus, similarly to DDX39—which is associated with telomere lengthening —DDX11 plays an important role in maintaining telomere length and stability in malignancies such as melanoma, lung cancer, and RCC." (PMID 34073906, 2021). "Of the nine putative proteomic biomarkers studied in an independent cohort using IHC, CDK4, ADAM10, SCAI, and DDX11 seem promising starting points for further investigation of their role in melanoma routine diagnostics." (PMID 40075679, 2025). "DDX11 expression has been reported upregulated during melanoma progression, which mirrored our proteomic and IHC analysis results." (PMID 40075679, 2025). "The helicase DDX11 has a role in chromatid cohesion, influencing proliferation and melanoma cell survival." (PMID 40075679, 2025). "Recently, high DDX11 expression was reported in melanomas, while suppressing DDX11 expression resulted in the inhibition of melanoma cell proliferation and cell death." (PMID 32332880, 2020). "In the future, we will perform an in vitro and in vivo study using DDX11 since ccRCC has similar tumor characteristics as melanoma." (PMID 31963294, 2020). "The findings of the study presented herein document that DDX11 is upregulated with progression from noninvasive to invasive melanoma, and that it is expressed at high levels in advanced melanoma." (PMID 23116066, 2012). "To gain insights into the cause(s) of the DDX11 siRNA-induced morphologic changes, we transfected melanoma cells with the DDX11 siRNA and 24 hr later prepared chromosome spreads that were stained with either fluorescent DAPI or Giemsa solution." (PMID 23116066, 2012). "Panel a, compared with the control, the DDX11 siRNA-transfected melanoma cells exhibited approximately 50% fewer chromosomes with closed arms, and about 50-60% more chromosomes with partially closed or open/separated arms." (PMID 23116066, 2012). "In this report, we present data, which document that the DEAD-box helicase DDX11, which is required for sister chromatid cohesion, is a crucial gatekeeper for melanoma cell survival." (PMID 23116066, 2012). "Performing immunohistochemistry and immunoblot analysis, we determined expression of DDX11 in melanoma tissues and cell lines." (PMID 23116066, 2012). "This difference in chromosome abnormality became even more apparent when the chromosome spreads of control siRNA and DDX11 siRNA-transfected melanoma cells were stained with Giemsa." (PMID 23116066, 2012). "Not pretreated with any agent to enrich for cells in mitosis, staining of WM1158 MGP melanoma cells with the DDX11 antibody served to show expression and localization of DDX11 during interphase (lane a) and the subsequent stages of mitosis (lanes b-e)." (PMID 23116066, 2012). "Following transfection of melanoma cells with a DDX11-specific siRNA, we conducted a qPCR analysis to determine downregulation of DDX11 in the transfected melanoma cells." (PMID 23116066, 2012). "The second and even more pertinent finding described herein is that inhibition of DDX11 expression leads to rapid and massive melanoma cell apoptosis." (PMID 23116066, 2012).